GCA (grancalcin)
Description:
Calcium-binding protein that may play a role in the adhesion of neutrophils to fibronectin. May play a role in the formation of focal adhesions.
Synonyms: GCL
Tractability: Small molecule: it has a high-quality binding pocket. Antibody: its Gene Ontology location is reachable by antibodies, with high confidence; UniProt places it where antibodies can reach, with medium confidence. PROTAC: its protein half-life has been measured.
Gene: Protein-coding gene on chromosome 2 (162,318,839 to 162,371,595, forward strand). Ensembl gene ENSG00000115271.
Subcellular location: Cytoplasm; Cytoplasmic granule membrane
Subcellular location (Human Protein Atlas): Cytosol; Plasma membrane
Pathways (Reactome):
Immune System: Neutrophil degranulation
Gene Ontology:
Molecular function: calcium ion binding; protein binding; protein heterodimerization activity; protein homodimerization activity
Biological process: membrane fusion
Cellular component: cytoplasm; cytosol; extracellular exosome; azurophil granule lumen; extracellular region; plasma membrane; membrane
Genetic constraint (gnomAD): Loss-of-function variants: 3 observed, 3.09 expected, observed/expected ratio (o/e) 0.97, 90% interval 0.42 to 1.85. That is too few expected variants to judge how well the gene tolerates losing a copy. Missense variants: 15 observed, 11.85 expected, observed/expected ratio (o/e) 1.27, 90% interval 0.84 to 1.83. Synonymous variants: 5 observed, 4.67 expected, observed/expected ratio (o/e) 1.07, 90% interval 0.54 to 1.84.
Homologues: Orthologues: chimpanzee GCA (98% identical), macaque GCA (92% identical), dog GCA (84% identical), mouse Gca (82% identical), pig GCA (80% identical), rat Gca (79% identical), guinea pig GCA (76% identical), tropical clawed frog gca (67% identical), zebrafish gca (58% identical), Caenorhabditis elegans clp-8 (19% identical), Caenorhabditis elegans tra-3 (14% identical), Caenorhabditis elegans clp-6 (12% identical), and 5 more. Paralogues in human: SRI (56% identical), CAPN8 (33% identical), PEF1 (33% identical), CAPN1 (33% identical), CAPN2 (32% identical), CAPN3 (32% identical), CAPN11 (31% identical), CAPN12 (29% identical), CAPN9 (29% identical), CAPN14 (24% identical), CAPNS1 (24% identical), CAPN13 (23% identical), and 8 more.
Diseases named in the same sentence as GCA in open-access papers:
GCA is named in the same sentence as 57 diseases in open-access papers, as found by Europe PMC text mining. Sharing a sentence is not in itself a finding about the gene and the disease. The quoted sentences say what the papers report.
cardiac hypertrophy (7 papers, 2009 to 2023). "Alternatively, deletion of either AT1 or AT2 markedly attenuates cardiac hypertrophy in natriuretic peptide receptor/guanylyl cyclase-A (GCA)-deficient mice." (PMID 22558183, 2012).
Obesity (5 papers, 2017 to 2025). Accumulation of substantial excess body fat. "Mice with depletion of GCA gene show resistance to skeletal deterioration caused by obesity and LPS‐induced chronic inflammation." (PMID 40349163, 2025). "To assess the association of GCA expression with obesity, we examined the expression levels of GCA in the bone." (PMID 38167327, 2024). "Moreover, in a study of 40 participants (20 obese and 20 healthy controls), we found that patients with obesity were associated with higher serum GCA levels." (PMID 40349163, 2025). "Herein, we find that GCA + (grancalcin) immune cells accumulate in the bone marrow and release a considerable amount of GCA into circulation during obesity." (PMID 38167327, 2024).
Sepsis (5 papers, 2021 to 2025). Sepsis is defined as life-threatening organ dysfunction caused by a dysregulated host response to infection. "Grancalcin (GCA) was chosen because it was the only gene with significantly more or less frequent splicing events in both sepsis and deceased groups and with one of the highest RNA-Seq read counts overall in both groups." (PMID 40992925, 2025). "Grancalcin (GCA) was chosen since it was the only gene with significant differential splicing events in both sepsis and deceased groups, each with 2,656 and 866 events, and with one of the highest RNA-Seq read counts overall in both groups." (PMID 40236428, 2025). "In contrast, a significant increase in the transcription of CLEC4D (C-type lectin domain family 4 member D), GCA (grancalcin), and ELANE (elastase, neutrophil expressed) was reported in the sepsis group as compared to the control." (PMID 34594344, 2021).
diabetes (2 papers, 2017 to 2024). "Skin‐perfusion pressure tests indicated that myeloid GCA deficiency significantly enhanced the skin blood‐flow rate 6 days post‐injury in animals with diabetes." (PMID 38308197, 2024). "Similarly, the intensity of CD31‐positive immunostaining was elevated in wound tissues of KO mice, suggesting that GCA deficiency enhanced angiogenesis during the wound‐repair process in diabetes." (PMID 38308197, 2024). "We used myeloid‐specific GCA‐knock‐out (CKO) mice to address the importance of bone marrow cell‐derived GCA in wound healing in diabetes." (PMID 38308197, 2024). "We have abundant reasons to believe that bone marrow cell‐derived GCA may function as a proinflammatory secretome in diabetes." (PMID 38308197, 2024). "In this study, we aimed to determine whether the genetic deletion of GCA in myeloid cells improves angiogenesis and wound healing in diabetes." (PMID 38308197, 2024).
Insulin resistance (2 papers, 2018 to 2024). Increased resistance towards insulin, that is, diminished effectiveness of insulin in reducing blood glucose levels. "As expected, we found that genetic deletion of GCA in myeloid cells attenuated adipose tissue inflammation and metabolic dysfunction in obese mice, whereas injection of recombinant GCA into mice caused adipose tissue inflammation and insulin resistance." (PMID 38167327, 2024).
prediabetes (2 papers, 2018 to 2024). "We further demonstrate that muscle-specific knockdown of GCA signaling (MKD-Gca) is sufficient to cause prediabetes." (PMID 39383215, 2024). "Together, these results indicate that ANP/GCA signaling controls muscle mitochondrial integrity and oxidative capacity in vivo and plays a causal role in the development of prediabetes." (PMID 39383215, 2024). "We further demonstrate that partial loss of ANP/GCA signaling specifically in skeletal muscle is sufficient to cause systemic insulin resistance and prediabetes." (PMID 39383215, 2024). "Here, we show that both systemic and skeletal muscle ANP/GCA deficiencies in mice promote metabolic disturbances and prediabetes." (PMID 39383215, 2024). "Here, we show that disruption of ANP/GCA signaling in skeletal muscle is sufficient to cause prediabetes." (PMID 39383215, 2024). "In summary, our data indicate that GCA haploinsufficiency, which phenocopies down-regulation of GCA observed in humans with obesity, impairs glucose homeostasis and promotes insulin resistance and prediabetes." (PMID 39383215, 2024).
Cholecystitis (1 paper, 2016). The presence of inflammatory changes in the gallbladder. "We found that serum levels of GCDCA, GCA and CA were abnormally higher in cholecystitis patients compared to the healthy people." (PMID 27624003, 2016).
chronic myeloid leukemia (1 paper, 2023). "In imatinib-resistant chronic-phase chronic myeloid leukemia (CML), upregulated GCA triggers TRAF6 ubiquitinase activity to induce K63-linked ULK1 ubiquitination and reduces K48-linked ubiquitination." (PMID 36646695, 2023).
depression (1 paper, 2023). "Notably among the hub genes identified, DNMT1, RRM2B and GCA have previously been shown to be associated with suicide or depression." (PMID 37398042, 2023).
fungal infections (1 paper, 2012). "Unlike LPL−/− neutrophils, grancalcin-deficient neutrophils were able to kill Staphylococcus aureus in vitro, and grancalcin was not required for other immune functions, such as macrophage recruitment to sites of inflammation or resistance to fungal infections." (PMID 22194750, 2012).
liver disease (1 paper, 2024). "Additionally, Pearson correlation analysis revealed that NAFLD Activity Score (NAS) and triglycerides (TG) were positively correlated with hepatic GCA mRNA levels, indicating that the severity of liver disease in patients with MASH was positively correlated with hepatic GCA expression." (PMID 39279458, 2024).
lung adenocarcinoma (1 paper, 2022). A carcinoma that arises from the lung and is characterized by the presence of malignant glandular epithelial cells. "In this case report, we identified a novel non-reciprocal ALK fusion: ALK-grancalcin (GCA) (A19: intragenic) and EML4-ALK (E20: A20) by next-generation sequencing (NGS) in a male lung adenocarcinoma patient who was staged as IIIB-N2 after surgery." (PMID 35070986, 2022).
memory impairment (1 paper, 2023). "Transplanting GCA+ immune cells or direct stereotaxic injection of recombinant GCA protein intensified amyloid plaque load and aggravated cognitive and memory impairments." (PMID 37949676, 2023).
meningioma (1 paper, 2020). A generally slow growing tumor attached to the dura mater. "Proteins involved in neutrophil degranulation, such as ARSA, GCA, FUCA1, PRTN3, ELANE, MNDA, and LCN2, were identified uniquely or with differential abundance in male meningiomas." (PMID 32587372, 2020).
osteosarcoma (1 paper, 2025). A usually aggressive malignant bone-forming mesenchymal neoplasm, predominantly affecting adolescents and young adults. "Bioinformatics analysis identified six exosome‐associated osteosarcoma genes (WNT5A, GCA, ANXA6, BIRC5, IL1β, and ARPC3) that could serve as potential biomarkers." (PMID 40616392, 2025). "The expression profiles of six core genes (WNT5A, GCA, ANXA6, BIRC5, IL1β, and ARPC3) were contrasted between the control and osteosarcoma groups." (PMID 40616392, 2025). "Other genes, including WNT5A (AUC = 0.935), GCA (AUC = 0.922), ANXA6 (AUC = 0.909), ARPC3 (AUC = 0.909), and IL1β (AUC = 0.766) also exhibited heterogeneous levels of predictive precision for detecting osteosarcoma." (PMID 40616392, 2025).
cancer (3 papers, 2016 to 2025). A tumor composed of atypical neoplastic, often pleomorphic cells that invade other tissues. "It encodes a protein that is constitutively activated in a variety of human cancers, including GCa, and plays critical roles in cancer cell proliferation, survival, metastasis and angiogenesis." (PMID 27049718, 2016). "Compared with the normal group, GCA, ANXA6, and BIRC5 in the cancer group were increased." (PMID 40616392, 2025).
gastrointestinal tumors (1 paper, 2021). "Important secondary BAs, such as TCDCA, GCA, GCDCA, and GDCA, have all been revealed as etiologic agents in gastrointestinal tumors." (PMID 34888230, 2021).
GCA also shares sentences with these, for which no sentence is quoted: Hypertension (11 papers); heart failure (5); cardiovascular diseases (3); tumor (3); fibrosis (2); glioma (2); liver fibrosis (2); renal fibrosis (2); achondroplasia (1); age (1); Age-Related Hearing Loss (1); albuminuria (1); Alzheimer disease (1); arteriopathies (1); arteritis (1); atherosclerosis (1); auditory neuropathy (1); Bacterial Infections (1); cardiomyopathy (1); dementia (1); Glucose intolerance (1); heart disease (1); Huntington disease (1); Hypervolemia (1); infection (1); insulinoma (1); lung carcinoma (1); melanoma (1); metabolic disorders (1); metabolic syndrome (1).
A further 10 diseases each share a sentence with GCA in 1 paper.